CCL2 (C-C motif chemokine ligand 2)
Diseases named in the same sentence as CCL2 in open-access papers (continued):
Sharing a sentence is not in itself a finding about the gene and the disease.
colon carcinoma (93 papers, 2010 to 2026). "The expression levels of both CCL4 and CCL2 were elevated in colon-cancer and lung adenocarcinoma tissues and were associated with shorter OS." (PMID 39996747, 2025). "CCL2 also causes tumor infiltration by type 1 cytotoxic γδ T lymphocytes in melanoma and by cytotoxic T lymphocytes in colon cancer." (PMID 33182504, 2020). "In a study on colon cancer, it was reported that during the initial stages of inflammation-associated colon cancer, bacterial lipopolysaccharide (LPS) regulates the expression of CCL2 in colonic epithelial cells, which in turn regulates the accumulation of monocyte-like macrophages (MLMs)." (PMID 39421736, 2024). "On the contrary, elevated CCL2 levels in colon cancer drives the recruitment and activation of myeloid cells, resulting in T cell suppression." (PMID 39566333, 2025). "Dihydroisotanshinone I, a bioactive compound in Salvia miltiorrhiza Bunge can hinder the recruitment of TAMs to colon cancer cells by inhibiting the secretion of CCL2 from TAMs." (PMID 40873588, 2025). "CCL2 expression, on the other hand, was mildly downregulated in primary colon cancer but increased in metastatic cancer (Log2FC = 1.06 ± 0.36)." (PMID 39409185, 2024). "Recent research has shown that in colon cancer, CCL2 influences the behavior of immune cells in the tumor microenvironment through its interaction with its primary receptor CCR2." (PMID 38791448, 2024). "In contrast to CCL2 treatment, 4T1-CM decreased ATP production in myotube cultures, which is consistent with studies on colon cancer models." (PMID 38973385, 2024). "Chronic inflammation is a key player in colon cancer, and the secretion of NFκB-controlled C-C motif chemokine ligand 2 (CCL2) by senescent stromal cells was proposed to promote carcinogenesis of the colon." (PMID 37958253, 2023). "A subcutaneous tumor model using Balb/c mice injected with CT26 colon carcinoma cells received either a saline or isotype control, anti-CCL2, 5-FU, or a combination of anti-CCL2 and 5-FU." (PMID 35461243, 2022). "The expression of CCL2 was increased in LPS-treated CT-26 (mouse colon cancer cell), which was consistent with our study that CCL2 expression was up-regulated in inflammatory states." (PMID 34925026, 2021). "Remarkably, upregulation of CPT1A in CAFs promotes the proliferation and invasion of colon cancer by enhancing the ability of CAFs to secrete CCL2, VEGF‐A, and MMP2." (PMID 33528867, 2021). "Cancer cell-derived CCL2 activates vascular endothelial cells to increase vascular permeability and increases cancer cell extravasation and metastasis in in vivo colon cancer model." (PMID 33297571, 2020). "CCL2 induces MDSC accumulation in evolving colonic tumors and enhances polymorphonuclear-MDSC immunosuppressive features, resulting in T lymphocyte suppression by polymorphonuclear-MDSCs in a STAT3-mediated manner." (PMID 33297571, 2020). "Knockout CCL2 in ApcMin/+ mice (ApcMin/+/CCL2−/−) inhibited tumor growth and immune infiltration in colon cancer." (PMID 32486076, 2020). "Accumulation of neutrophils/PMN-MDSCs in small intestinal and colon tumors of Apc1638N/+ mice correlated with increased expression of CCL2 compared to normal intestinal tissue with slightly higher expression in colon tumors." (PMID 31681563, 2019). "Supportive evidence for the immune-suppressing function of CCL2 via MDSCs was gained in a murine ApcMin/+ in vivo model of colon cancer in which anti-CCL2 Ab reduced tumor number compared to isotype control Ab." (PMID 31921102, 2019). "Although MC38 colon cancer cells release high levels of CCL2 and recruit MAMs via a CCR2-dependent manner to the liver, these cells produce CCL20 and recruit TAMs via a CCR6-dependent mechanism to primary tumors established by subcutaneous injection." (PMID 30483271, 2018).
colon carcinoma (continued). "Accordingly, increased expression of additional STAT3 target genes critically involved in colon cancer progression, i.e., cytokine CCL-2 and the oncogene Myc, was detected in Sdc1-KO tumors (middle, right, 4D)." (PMID 28350804, 2017). "However, it has been demonstrated in mouse models of colon cancer lung metastasis that CCL2-induced high expression of Ly6C monocytes is a necessary but not sufficient condition for effective metastasis." (PMID 41341593, 2025). "Furthermore, studies have shown that CCL2 synergistically with lipopolysaccharide (LPS) can activate the tumoricidal properties of macrophages, thereby reducing lung metastasis of colon cancer." (PMID 41341593, 2025). "We confirmed that miR-126 OE downregulated CCL2 expression in colon cancer cells in vitro." (PMID 39419989, 2024). "Another work in a CT26 murine colon carcinoma model also suggests that blockade of CCL2 (or macrophage chemoattractant protein-1, MCP-1) is sufficient to reduce circulating monocytes-derived TAMs in TME and has the ability to modestly alter tumor growth to treatment." (PMID 37443711, 2023). "Future studies using a chemically-induced orthotopic model of colon cancer using anti-CCL2 in combination with 5-FU while using DRS to monitor treatment response can provide clinicians more clinically relevant evidence of using cytokine-targeted therapy in CRC." (PMID 35461243, 2022). "Losartan and its primary metabolite, EXP-3174, inhibit CCL2-mediated monocyte recruitment to the metastatic site through the inhibition of CCL2-induced Erk1/2 activation and significantly reduce the metastatic burden in breast and colon cancer models." (PMID 33297571, 2020). "In support of this hypothesis, steady‐state mRNA CCL2 levels were previously shown to be significantly elevated in colon cancer tissues as compared to normal colon." (PMID 31545552, 2019). "Moreover, colon cancer cell-derived CCL2 activates CCR2 on endothelial cells, thereby enabling efficient cancer cell extravasation." (PMID 31501414, 2019). "Notably, CCL2 promotes the metastasis of several cancers, including nasopharyngeal carcinoma, bladder cancer, thyroid carcinoma, and colon cancer." (PMID 28157698, 2017). "In the CT26 colon cancer model the presence of nitration of the CCL2 chemokine diminished CD8+ T cell infiltration and may attract MDSC into the tumor microenvironment." (PMID 29133913, 2017). "Furthermore, CatS and CCL2 show a strong clinical correlation in brain, breast and colon tumours." (PMID 26358505, 2015). "In the course of this carcinogenesis process, CCL2 was detected mainly in mononuclear cells, especially macrophages infiltrating the lamina propria and submucosal regions, while it was detected also in endothelial cells at the early stages and in colon cancer cells at the later phase." (PMID 24212934, 2011). "Ccl2-knock down was confirmed in Lewis Lung Carcinoma LLC1.1 and colon carcinoma MC38-GFP cells by real-time PCR." (PMID 39566333, 2025). "The increase of the expression of TLR4 and the increase of the production of CCL2, COX-2, PGE2, and TNF-α compromise the regeneration of the mucosa, with consequent tissue damage that over time can lead to the development of cancer of the colon." (PMID 35204289, 2022). "The in vitro results suggested that flagellin promotes the survival of colon cancer cells by inhibiting apoptosis and by inducing inflammatory cytokines, such as CCL2/MCP-1, as well as necrosis." (PMID 31731747, 2019). "Here, we have shown that in MC38 colon carcinoma cells, targeting of CatS (using shRNA) or gamma secretase (using DAPT), results in the attenuation of CCL2 protein expression, in agreement with previous observations." (PMID 26358505, 2015). "Abundant CCL2 is detected in colon tissues, and CCL2 blockade reduces the infiltration of CCR2-positive COX-2 expressing monocytes/macrophages and eventually colonic tumor development and progression." (PMID 24966464, 2014).
colon carcinoma (continued). "Considering that the tumor monocyte population decreased upon EGC depletion, we speculate that CRC EGC-derived chemokines (i.e., CCL2 and CXCL5) could also promote the infiltration of monocytes in the colonic tumor site." (PMID 39030280, 2024). "In addition, CCR2—the most common receptor for CCL2 —promotes stabilization and translocation of β-catenin via AKT/GSK3β signaling in colon cancer cells." (PMID 35562953, 2022). "CCL2 and CXCL8 induces epithelial-mesenchymal transition in colon cancer and bladder cancer." (PMID 31488217, 2019). "In addition to CCL2, CXCR2 ligands including CXCL1, CXCL2, CXCL3, and CXCL8 produced by CRC cells and neutrophils themselves were found to be responsible for recruitment of CXCR2+ neutrophils/PMN-MDSCs to colon tumors." (PMID 31681563, 2019). "Moreover, CCL2 antagonists decreased intracolonic macrophage infiltration and COX-2 expression together with attenuated neovascularization, even when given after multiple colon tumors have developed." (PMID 24212934, 2011).
pneumonia (88 papers, 2009 to 2025). An acute, acute and chronic, or chronic inflammation focally or diffusely affecting the lung parenchyma, caused by an infection in one or both of the lungs (by bacteria, viruses, fungi, or mycoplasma.). "Mechanisms of tissue injury in SARS-CoV-2-induced pneumonia share some aspects with influenza virus infection, but IL-1β seems to play more important roles along with CCL2 and impaired type I interferon signaling might be associated with delayed virus clearance and disease severity." (PMID 33062077, 2020). "Nevertheless, the impact of S1P receptor ligands on CCL2 was established using influenza virus infection preclinical models, and patients with a high risk of severe disease display low S1P levels in bacterial pneumonia, arguing that our findings may extend to different pneumonia etiologies." (PMID 40025871, 2025). "Significant differences between genotypes that exceeded 1.5-fold in male mice with S. pneumoniae pneumonia include higher concentrations of IFNγ, IL-12 (p40), IL-17A and MCP-1 (CCL2) in HRB-Mertk-/- compared to wild type males." (PMID 40238852, 2025). "In our study, we performed a correlation analysis in the group of patients with HIV and pneumonia, evaluating the cytokines IL-6, IL-17A, MCP1/CCL2, PAI1, IL-1β, and VEGF/VPF in relation to key parameters of lung function." (PMID 38251391, 2024). "In agreement, increased CCL2 levels have been reported to improve the clearance of pathogens and the survival of S. pneumonia infected mice." (PMID 35734179, 2022). "During Streptococcus pneumonia infection, CCL2-dependent lung exudate macrophages and conventional dendritic cell are recruited to contain the progression of pneumonia and contribute to lung protection." (PMID 31064097, 2019). "Hyperactivation of the proinflammatory cytokines IL-6, CXCL8/IL-8, CCL2/MCP-1 and sTNFR-1 was found in pH1N1 pneumonia (2–15 times normal) and in complicated seasonal influenza, but not in milder pH1N1 infections." (PMID 22022504, 2011). "There was sustained activation of the proinflammatory cytokines (IL-6, CXCL8/IL-8, CCL2/MCP-1, sTNFR-1) in severe pH1N1 pneumonia; the CXCL10/IP-10, CXCL9/MIG and IL-17A responses remained largely suppressed during the hospital course." (PMID 22022504, 2011). "Research indicates that the cytokine storms in severe pneumonia may be involved in high levels of interleukin (IL)-6 and monocyte chemoattractant protein-1/C-C motif chemokine ligand 2 (MCP-1/CCL2)." (PMID 36135185, 2022). "The CXCL8 and CCL2 cytokines, also known as chemokines, were abundant in all the pneumonia groups." (PMID 34829225, 2021). "Notably, only after an early therapy start were significant differences between ampicillin-treated and solvent-treated mice with pneumonia observed for CCL2." (PMID 30382866, 2018). "In Baladi goats with pneumonia and healthy control group, PCR-DNA sequencing revealed SNPs linked to pneumonia susceptibility and resistance in immunological genes (SLC11A1, CD-14, CCL2, TLR1, TLR7, TLR8, TLR9, defensin, SP110, SPP1, BP1, A2M, ADORA3, CARD15, IRF3, and SCART1)." (PMID 40221769, 2025). "The immune genes’ mRNA levels in goats (SLC11A1, CD-14, CCL2, TLR1, TLR7, TLR8, TLR9, defensin, SP110, SPP1, BP1, A2M, ADORA3, CARD15, IRF3, and SCART1) varied between the healthy and infected goats with pneumonia." (PMID 40711280, 2025). "Similar to CCL2, in Xue’s study, the serum levels of CXCL13 were significantly lower in the patients with pneumonia and the normal controls than in the IIP group (including IPAF patients)." (PMID 35011819, 2021). "We next assessed the contribution of IL-1β, CXCL1, CCL2, and CCL7 to the recruitment of neutrophils during S. pneumoniae pneumonia using specific neutralizing Abs administered intranasally." (PMID 25948816, 2015).
pneumonia (continued). "In a pneumonia model of intratracheal Pseudomonas aeruginosa intraperitoneal administration of anti-MCP1/CCL2 aggravated lung tissue injury and did not decrease infiltrated cells in the alveolar space 48 h after infection." (PMID 40858671, 2025). "Meanwhile, the results of molecular docking also exposed the active ingredients of YPFG could tack a part in modulating the progression of pneumonia via MMP9, CCL2, IL-1B, IL-6, CXCL8, and TNF." (PMID 36285159, 2022). "Through PCR-DNA sequencing in Baladi goats with and without pneumonia, SNPs linked to pneumonia susceptibility and resistance were discovered in the immunological (SLC11A1, CD-14, CCL2, TLR1, TLR7, TLR8, TLR9, defensin, SP110, SPP1, BP1, A2M, ADORA3, CARD15, IRF3, and SCART1) genes." (PMID 40711280, 2025). "However, the general downregulation of expression of CCL2, CCL3 and CCL5 in the pneumonia cases may be related to decreases in numbers of peripheral T and B lymphocytes." (PMID 36119044, 2022). "Increased transcription of chemokine receptors CCR2 (CCL2/monocyte chemoattractant protein-1 (MCP-1) receptor) and CCR5 (CCL3/MIP-1A receptor) were observed, indicating that these inflammatory signals were activated, but receptors XCR1, CCR4, and ACKR3 were downregulated in the pneumonia group." (PMID 36119044, 2022). "The levels of immunological genes (SLC11A1, CD-14, CCL2, TLR1, TLR7, TLR8, TLR9, defensin, SP110, SPP1, BP1, A2M, ADORA3, CARD15, IRF3, and SCART1) vary in goats with and without pneumonia." (PMID 40221769, 2025). "Real-time PCR was conducted to quantify the expression levels of immunological markers (SLC11A1, CD-14, CCL2, TLR1, TLR7, TLR8, TLR9, β defensin, SP110, SPP1, BP1, A2M, ADORA3, CARD15, IRF3, and SCART1) in Baladi goats with and without pneumonia resistance." (PMID 36977224, 2023).
steatosis (86 papers, 2009 to 2026). Increased lipid within the cytoplasm of cells. "Conversely, in the development of nonalcoholic steatohepatitis, there is an upregulation of CCL2 and its receptor in the liver, facilitating macrophage recruitment, inflammation, steatosis and fibrosis, as well as in adipose tissue." (PMID 40070835, 2025). "CD47 deficiency enhances NF-κB activation, elevates IL-1β, TNFα, IL-6, reduces IL-10, increases CCL2 and macrophage infiltration, leading to exacerbated steatosis, inflammation, and fibrosis." (PMID 40630093, 2025). "Conversely, genetic depletion or pharmacological inhibition of CCL2 in mice has been shown to improve steatosis progression, alleviate hepatic inflammatory response, and reduce liver injury." (PMID 39568749, 2024). "Elevated CD36, IGFBP1 (insulin-like growth factor–binding protein 1), and chemokine (C–C motif) ligand 2 (CCL2) expression leads to steatosis and inflammation in the Wtap-HKO livers." (PMID 37777158, 2023). "Elevated serum CCL2, a pro-inflammatory cytokine, was observed in the FS-90 group and CCL2 has been shown to promote steatosis during liver injury." (PMID 36235565, 2022). "When upregulated, CCR2 can induce macrophage accumulation, inflammation, fibrosis and steatosis and the CCL2/CCR2 axis can influence cell growth, angiogenesis, invasion and metastasis." (PMID 34251980, 2021). "With progression of steatosis and balloon-like degeneration of liver cells, KCs secrete chemokines, including CCL2 and MCP-1, through the infiltration of monocytes, thereby increasing the production of macrophages." (PMID 34095305, 2021). "The N800 treatment induced high levels of serum CCL2 and IL-6, accompanied by the appearance of steatosis in both propacetamol-poisoned and normal mice." (PMID 33809388, 2021). "Ccl2 overexpression resulted in steatosis, decreased AMPK activity and altered mitochondrial dynamics in the liver." (PMID 32686726, 2020). "Particularly, the monocyte chemoattractant protein-1 (MCP-1), expressed by the gene Ccl2, is a key factor driving liver macrophage infiltration and steatosis." (PMID 32392802, 2020). "In the liver, Ccl2 overexpression resulted in steatosis, decreased AMPK activation, and upregulation of mTORC1." (PMID 32686726, 2020). "Conversely, knock-out of Ccl2 or its receptor Ccr2, improves insulin sensitivity and prevents steatosis." (PMID 19513120, 2009). "As an immune mediator, IL-1β might not only promote fat accumulation in the liver and induce hepatocyte steatosis but also activate stellate cells and amplify inflammation-induced Ccl2, Tnf, and Il1b expression." (PMID 36426356, 2022). "High chemokine (C-C motif) ligand 2 (CCL2)/monocyte chemoattractant protein 1 (MCP1) levels in NASH may be important for the transition from simple steatosis to NASH." (PMID 36189280, 2022). "Following the development of steatosis, hepatocytes and Kupffer cells secrete chemotactic agents, including chemokine C-C motif ligand 2 (CCL2, also referred to as monocyte chemotactic protein-1, MCP-1), thus increasing the liver macrophage pool through monocyte infiltration." (PMID 30787925, 2019). "In addition, CCL2 has also been shown to be increased in livers of mice with high-fat diet induced steatosis." (PMID 27454769, 2016). "Histological features were confirmed by real‐time PCR analyses, showing alcohol‐induced upregulation of the chemokines MCP‐1/CCL‐2 and CXCL1, along with the cytokine TNF‐α, implicated in hepatic inflammation, and of PPARγ that promotes both hepatic inflammation and steatosis." (PMID 39921321, 2025). "Previous studies have shown that increased hepatic CCL2 recruits CCR2-positive monocytes, exacerbating inflammation, fibrosis, and steatosis in MASLD patients." (PMID 40507104, 2025). "RUNX1 target genes, CCL2 and PIK3CA significantly correlated to NAS, steatosis, inflammation grade and fibrosis score, NOS3 to NAS and inflammation grade and PRKCE to NAS and steatosis grade." (PMID 31635436, 2019).